ZNF708 (zinc finger protein 708)
Description:
May be involved in transcriptional regulation.
Synonyms: KOX8; ZNF15; ZNF15L1
Tractability: PROTAC: ubiquitination databases record sites on it.
Gene: Protein-coding gene on chromosome 19 (21,284,033 to 21,329,425, reverse strand). Ensembl gene ENSG00000182141.
Subcellular location: Nucleus
Pathways (Reactome):
Gene expression (Transcription): Generic Transcription Pathway; Regulation of endogenous retroelements by KRAB-ZFP proteins
Gene Ontology:
Molecular function: DNA-binding transcription factor activity; RNA polymerase II cis-regulatory region sequence-specific DNA binding
Biological process: regulation of DNA-templated transcription
Cellular component: nucleus
Genetic constraint (gnomAD): Loss-of-function variants: 43 observed, 42.51 expected, observed/expected ratio (o/e) 1.01, 90% interval 0.79 to 1.3. The upper end of that interval is the gene's LOEUF score, 1.3, which puts it in group 5 of 6, group 1 being the genes least tolerant of losing a copy. Missense variants: 551 observed, 630.88 expected, observed/expected ratio (o/e) 0.87, 90% interval 0.81 to 0.94. Synonymous variants: 184 observed, 203.45 expected, observed/expected ratio (o/e) 0.9, 90% interval 0.8 to 1.02.
Homologues: Orthologues: chimpanzee ZNF708 (99% identical), macaque ZNF708 (98% identical). Paralogues in human: ZNF724 (77% identical), ZNF254 (74% identical), ZNF726 (74% identical), ZNF85 (74% identical), ZNF728 (73% identical), ZNF43 (72% identical), ZNF493 (70% identical), ZNF429 (69% identical), ZNF93 (69% identical), ZNF90 (69% identical), ZNF681 (69% identical), ZNF676 (67% identical), and 164 more.
Diseases named in the same sentence as ZNF708 in open-access papers:
ZNF708 is named in the same sentence as 6 diseases in open-access papers, as found by Europe PMC text mining. Sharing a sentence is not in itself a finding about the gene and the disease. The quoted sentences say what the papers report.
breast tumors (1 paper, 2023). "In their analysis, the genomic region harboring ZNF714 (and other genes, including its closest neighbors: ZNF85, ZNF430, ZNF431, ZNF708) was found to undergo copy number gains in estrogen-negative (ER-) breast tumors as compared to ER+ tumors." (PMID 37958512, 2023).
Headache (1 paper, 2018). Cephalgia, or pain sensed in various parts of the head, not confined to the area of distribution of any nerve. "We identified numerous genes associated with headache, both temporal and other types: POFUT2 in CD4 cells, and SLC35F6, HTD2, ZNF708, KLRC4-KLRK1 and JMJD7 in CD8 cells." (PMID 30037347, 2018).
ZNF708 also shares sentences with these, for which no sentence is quoted: glioma (1 paper); muscular dystrophy (1); prostate carcinoma (1); tumor (1).